PPARG (peroxisome proliferator activated receptor gamma)
Diseases named in the same sentence as PPARG in open-access papers (continued):
Sharing a sentence is not in itself a finding about the gene and the disease.
cancer (continued). "The significance of PPARG in cancer development and the potential for therapeutic targeting of PPARG remain elusive." (PMID 38044948, 2023). "Considering the complex role of PPARγ in metabolic regulation and cancer progression, selective PPARγ modulators for cell- or organ-specific modulation are a promising area for future studies." (PMID 36998980, 2023). "In this study, we conducted a comprehensive pan-cancer analysis of PPARG expression using various types of cancer obtained from public databases." (PMID 38044948, 2023). "Regarding cancer cell proliferation, multiple cyclins and cyclin-dependent kinases (CDKs) are positive regulators of cell cycle progression, and activated PPARγ promotes cyclin D1 ablation and induces cell arrest." (PMID 37251321, 2023). "Through this modification, RNF20 reduces cell size by inactivating PPARγ in adipocytes and suppresses metastasis by regulating SREBP1c in cancer cells." (PMID 38068817, 2023). "Finding BRAF mutations or PPARG, NTRK1, NTRK3 and ALK fusions were strong predictors of a higher risk of cancer (approaching 100%) while other mutations like RAS, PTEN and EIF1AX or THADA fusions were associated with a significant but lower risk of cancer." (PMID 37510219, 2023). "Peroxisome proliferator-activated receptor gamma (PPARG), a key transcription factor involved in lipid metabolism and glucose homeostasis, has been implicated in various types of cancer." (PMID 38044948, 2023). "The correlation between PPARG and TMB, MSI, and MMRs also demonstrated a close association between PPARG and TME in human cancers." (PMID 38044948, 2023). "The PPARG mRNA expression levels in tissue samples with cancer and paraneoplasm were evaluated using the TIMER 2.0 and TCGA databases." (PMID 38044948, 2023). "The results of our study provide strong support for the potential role of PPARG as a promising prognostic biomarker and immunotherapeutic target across various types of cancer." (PMID 38044948, 2023). "To research PPARG expression in pan-cancer and BC, we obtained RNAseq data and corresponding clinical information from 33 cancer types and 10,228 samples from TCGA and GTEx databases." (PMID 37334066, 2023). "Western blot analysis showed that the expression of PPARγ, clathrin, and β-adaptin was upregulated in both cancer cells by Δ9-THC treatment." (PMID 37837516, 2023). "In conclusion, we developed novel instruments for PPARG, ABCC8 and GLP1R using strict validation protocols and evaluated the association of genetically proxied perturbation of these targets with risk of cancer." (PMID 37171501, 2023). "As a transcription factor, PPARG is involved in the regulation of lipid anabolism and glycolysis to meet the energy demands of cancer cells." (PMID 38044948, 2023). "This study aims to comprehensively investigate PPARG expression in human cancers and its impact on prognosis and clinical significance." (PMID 38044948, 2023). "In HCC, the activation of the PPARγ signaling pathway can lead to the promotion of cancer cell growth and proliferation, and it can also create a pro-tumorigenic environment." (PMID 37763758, 2023). "It has been established that in cancer cells, the activation of PPARG leads to cell cycle arrest, suppression of cell proliferation, and increased apoptosis." (PMID 38044948, 2023). "Data in the literature on knockout mouse models suggest a protective role for PPARγ in keratinocyte-derived carcinoma." (PMID 37048080, 2023). "The predominant use of in vitro cell culture studies is limited in its elucidation of the biological relevance of PPARγ in cancer, as complex gene–gene and gene–environment interactions are not considered." (PMID 35954274, 2022). "Nuclear receptors, especially PPARγ, hold potential as key factors for anti-cancer therapies, as they function as pro-differentiation factors, reducing the proliferation capacity of tumorigenic cells." (PMID 36142452, 2022).
cancer (continued). "Another study showed that Da Ea (ethyl acetate extract of D. altaica), which has anti-cancer effects, increased PPARγ expression levels, induced apoptosis and S phase cell cycle arrest, which prevented the proliferation of ECA 109 cells." (PMID 36142861, 2022). "FZD9 also plays a key role in the activity of iloprost, where it is required for iloprost’s activation of PPARγ and downstream anti-cancer signaling." (PMID 35924166, 2022). "Rationally activation of PPARγ is required for glucose and lipid metabolism to meet the high demands of energy for cancer cell growth, invasion and migration." (PMID 35922782, 2022). "Spiegelman and colleagues demonstrated exciting results in various cancer types by manipulating PPARγ." (PMID 36034865, 2022). "Following activation by its ligands 15d-PGJ2, PPARγ heterodimerizes with RXRα and exerts antigrowth effects in cancer cells." (PMID 35406808, 2022). "The PPARγ agonists, thiazolidinediones, are known to induce apoptosis in a number of different cell lines, including cancer cell lines." (PMID 36074574, 2022). "Recent research has shown that activation of PPARγ can inhibit cancer cell proliferation, promote cell cycle arrest, reduce cancer cell migration and invasion, and inhibit angiogenesis." (PMID 36364935, 2022). "The network results demonstrated that seven anti-HCC core targets (CASP3, EGFR, ERBB2, mTOR, MMP9, HIF1A, and PPARG) followed the pathways in cancer (degree 7)." (PMID 35959427, 2022). "Upregulation of PPARγ negatively impacts on the cancer stem cell population by impeding the activity of these inflammatory growth factors." (PMID 35159385, 2022). "PPARγ agonists have shown promising results in impeding cancer and reducing cancer stem cell population." (PMID 35159385, 2022). "NSAIDs were reported to have beneficial effects on colon metastasis inhibition through their suppression of cancer stem cells, mediated through the suppression of Cox-2 and the activation of PPARγ." (PMID 35954274, 2022). "FABP5 was demonstrated to promote angiogenesis through activating the IL6/STAT3/VEGFA pathway in HCC, or transporting excessive levels of fatty acids into the nucleus of the cancer cells to activate PPARγ thereby up-regulating the expression of VEGF." (PMID 35445019, 2022). "Seven anti-HCC core targets (CASP3, EGFR, ERBB2, mTOR, MMP9, HIF1A, and PPARG) followed the pathways in cancer." (PMID 35959427, 2022). "As it is assumed that the anticancer activity of TZDs is mediated through PPARγ activation, they have been clinically tested against human cancers that express high levels of PPARγ." (PMID 35215339, 2022). "The expression of PPARγ at both protein and gene level showed positive predictive value to malignant tumor metastasis." (PMID 35922782, 2022). "Based on the outcomes of all these studies, it is therefore impossible to recommend PPARγ modulation to induce cancer-cell death." (PMID 35954274, 2022). "TZDs activate PPARγ to induce cell cycle arrest and apoptosis and inhibit cancer cell proliferation and invasion." (PMID 35252271, 2022). "This further adds to the complexity regarding the role of PPARγ in cancer, which depends on the stage of cancer development." (PMID 35954274, 2022). "PPARγ promotes the growth of this cancer type via the activation of lipid signaling pathways, i.e., the upregulation of fatty-acid synthase, acetyl-CoA carboxylase, and ATP citrate lyase." (PMID 35954274, 2022). "A recent study examined PPARγ rs1801282 SNV in multiple human cancer cell lines, and a heterozygous CG genotype was detected in AGS and Caki-1 cancer cell lines." (PMID 36587194, 2022). "PGC1α inhibits the aerobic glycolysis of cancer cells through PPARγ-dependent inhibition of the WNT/β-catenin pathway." (PMID 35954274, 2022).
cancer (continued). "For instance, in adipocytes and cancer cells, ER receptor has been shown to directly interact with peroxisome proliferator activated receptor gamma (Pparγ), a major driver of lipid storage and adipogenesis, to block its transcriptional activity." (PMID 35721736, 2022). "Aside from the established properties of PPARγ, the relevance of PPARγ to the regulation and differentiation of cancer cell growth is increasingly recognized." (PMID 35922782, 2022). "PPARγ agonists (e.g., TZDs) have been shown to induce apoptosis in various cancer cells including lymphoma, multiple myeloma, bladder, gastric, esophageal, pancreatic, hepatoma, colon, breast, brain, and lung cancer cells." (PMID 35566291, 2022). "According to above analysis, PPARG can regulate the homeostasis of the intestinal environment through inflammation, and stigmasterol can exert anti-inflammatory and anti-cancer effects." (PMID 35672755, 2022). "Surprisingly, Sarraf and colleagues also observed high PPARγ levels in colon tumors, a cancer type originating from transformed epithelial cells." (PMID 36034865, 2022). "15d-PGJ2, an endogenous ligand of PPARγ, induces PPARγ-dependent or independent cell apoptosis in cancer cells and regulates the inflammatory responses." (PMID 34997457, 2022). "In contrast, Telmisartan, an angiotensin II receptor blocker (ARB), was found to inhibit cancer cell proliferation and induce apoptosis through the activation of PPARγ." (PMID 35954274, 2022). "In turn, PPARγ was found to regulate adipocyte differentiation, improve IR and be involved in the development of inflammation, autoimmune diseases, and cancers." (PMID 35328822, 2022). "Troglitazone and ciglitazone inhibited aerobic glycolysis, induced SIRT1 expression and endoplasmic reticulum stress in cancer cells, and induced autophagy and apoptosis independently of PPARγ." (PMID 35954274, 2022). "Recent studies point to the role of PPARγ in different aspects of cancer cell growth and metabolic reprogramming." (PMID 35922782, 2022). "In conclusion, DHA-PC and EPA-PC have great potential for cancer therapy, and the antineoplastic effects involve the activation of PPARγ." (PMID 36364935, 2022). "EGFR, KIT, MET, PPARG, and STAT5A were enriched in the Pathways in cancer, CAV1, EGFR, and MET were enriched in the Proteoglycans in cancer, and MET and PPARG were enriched in the Transcriptional misregulation in cancer." (PMID 35063044, 2022). "In recent years, there has been a growing debate about the common biological mechanisms in metabolic diseases and cancer, and genes such as PPARγ aroused major interest." (PMID 34439147, 2021). "Mφ exposed to irradiated apoptotic cancer cells activate peroxisome proliferator-activated receptor gamma (PPARγ) and increase the expression of phosphatase and tensin homolog (PTEN) in Mφ-EVs." (PMID 34975877, 2021). "Many early phase clinical trials have been conducted to examine the clinical feasibility of PPAR agonists, particularly PPARα and PPARγ agonists, against a wide range of cancers." (PMID 33946986, 2021). "The unique property of nuclear receptor peroxisome proliferator‐activated receptor‐γ (PPARγ) in transmitting the anti‐survival signals of the chemotherapeutic drugs has fired the enthusiasm into the application of this receptor in cancer treatment." (PMID 34549887, 2021). "Taken together, these results underscore the relevance of ILC2s and PPARγ in fostering cancer cell progression and subsequent metastatic potential." (PMID 33953160, 2021). "PPARγ, as a nuclear receptor transcription factor, regulates mitochondrial function and participates in cancer cell metabolism, oxidative redox and biosynthesis." (PMID 35186942, 2021). "PPARγ, as a modulator of cellular differentiation and regulator of tumorigenesis, was found to be expressed in many different types of cancer cells and its activation by agonists leads to either cell proliferation inhibition or cancel cell apoptosis." (PMID 34946618, 2021).
cancer (continued). "This anti-cancer effect seems to be mediated by the activity of the ligand-activated PPARγ complex, as a novel PPAR responsive element has been predicted on the CXCR4 promoter." (PMID 34834449, 2021). "The idea of using TZDs for treatment of cancer has originated from the fact that the expression level of PPARγ nuclear receptors differs in the normal and transformed tissues, and are involved in cell proliferation." (PMID 34535145, 2021). "The activation of PPARγ in cancer cells stimulates adipogenesis and disrupts the Hippo-YAP signaling pathway to force terminal differentiation and suppress proliferation." (PMID 33946986, 2021). "The MMOC allowed identification of numerous cancer chemopreventive agents such as resveratrol, deguelin, brassinin, sulforaphan analogs, certain vitamin D analogs (, and PPARγ agonists such as troglitazone, among others." (PMID 34884959, 2021). "An increasing number of studies have revealed that PPARγ, one of peroxisome proliferator‐activated receptors, plays essential role in cancer metabolism." (PMID 33797188, 2021). "Superparamagnetic iron oxide nanoparticles functionalized with conjugated linoleic acid have been shown to increase PPARγ activity, subsequently triggering necrotic cell death in cancer cells." (PMID 33946986, 2021). "In specific types of cancers, including bladder and colon carcinoma, the activation of PPARγ resulted in genomic alterations that promoted tumorigenesis." (PMID 34067944, 2021). "Although both ERs and PPARγ belong to the family of nuclear receptor proteins and both can regulate thyrocyte proliferation and growth, there are very few studies on the relationship between ERs and PPARγ in cancer cells." (PMID 34557159, 2021). "The PPARγ agonist pioglitazone inhibited EGFR/MDM2 signaling-mediated PPARγ degradation and increased cancer cell sensitivity to chemotherapy drugs." (PMID 33935743, 2021). "Considering the pleiotropic nature of PPARγ and DNMT1 there is a need to investigate if their interaction also plays a role in the association between metabolism and cancer." (PMID 34439147, 2021). "Experiments in the androgen-sensitive LNCaP cell line demonstrated that this compound induces cancer cell death through a mechanism that involves PPARγ and CB1R activation as well as oxidative stress." (PMID 33498245, 2021). "These PPARγ activities create a “friendly” TME for cancer survival, which also coincides with the functional trajectory of macrophage PPARβ/δ." (PMID 33946986, 2021). "PPARγ agonists such as the anti-diabetic drug thiazolidinedione suppress the Wnt/β-catenin pathway and cancer-related proliferation pathways." (PMID 33525605, 2021). "To date, it is known that several cannabinoids can activate these receptors (e.g., PEA, OEA activate PPARα; e.g., THC, AEA and 2-AG activate PPARγ) and that PPARs have an involvement in cancer (e.g., colon, ovarian, breast and prostate cancer)." (PMID 34943903, 2021). "Another pitfall in PPAR cancer research is that current drug development and research attention highly skew towards PPARα and PPARγ." (PMID 33946986, 2021). "Further, PPARγ blockade in ILC2s disrupts their pro-tumoral effect induced by IL-33-secreting cancer cells." (PMID 33953160, 2021). "Since the identification of the PPARG gene in the early 1990s the role of PPARγ in cancer has extensively been studied in many different human cancer cells and animal models." (PMID 33716977, 2021). "PPARγ antagonists have also been seen as a potential therapy for cancer, as they have demonstrated antiproliferative effects on cancer cells." (PMID 35003101, 2021). "The non-intoxicating phytocannabinoid CBD has also been reported to exert antitumor actions through CB1R and PPARγ in specific types of cancer." (PMID 33498245, 2021). "An association of Arid5a-regulated molecules, such as IL6, Tbet, Stat3, Ox40, and Pparγ, has been widely studied in various cancers and tumor models." (PMID 35126382, 2021).
cancer (continued). "Apart from protein–protein interactions and co-expression in multiple cancer types, we exclusively described a prognostic role for PPARγ in UM." (PMID 34439147, 2021). "PPARγ is expressed in many cancers including those of the colon, breast, and prostate, and PPARγ ligands are generally found to have anti-proliferative effects in these cells." (PMID 37073266, 2021). "We roughly eliminated the possibility of PPARβ/δ and PPARγ being involved in cancer stemness using GSK3787/GW9662, and suggested that PPARα is necessary for the maintenance of stemness in pancreatic and colorectal CSCs." (PMID 33466690, 2021). "Surgery appears to be recommended when a molecular alteration is detected, particularly BRAF or PAX8/PPARγ which are highly specific for cancer." (PMID 32638211, 2021). "Pretreatment with ruxolitinib significantly inhibited the increase in aP2 and PPARγ expression in the cancer cathetic mice serum-treated ST2 cells under adipogenic differentiation conditions." (PMID 33801569, 2021). "Peroxisome proliferator-activated receptor gamma-dependent downregulation of CXCR4 in cancer cells slows the rate of metastasis." (PMID 33771976, 2021). "Emerging evidence suggests that an interaction between PPARγ and DNMTs (DNA methyltransferase) plays a role in cancer that is yet to be defined." (PMID 34439147, 2021). "One possible reason behind that confliction is that some ARBs, such as telmisartan, are able to activate the Peroxisome Proliferator-Activated Receptor-gamma’s (PPAR-γ) signalling, which controls the proliferation of cancer and promotes apoptosis." (PMID 34539580, 2021). "For the further study, we are trying to examine that rosiglitazone, FDA approved hypoglycemic agent as PPARγ agonists, has anti-cancer activity against RCC through inhibition of JAK2 phosphorylation." (PMID 33917914, 2021). "The increase in PPARγ observed is in agreement with an anti-proliferative role of this transcription factor already reported in different cancers." (PMID 33525605, 2021). "In a considerable number of studies, it has been claimed that the over expression of PPARγ in cancer cells is a determining factor in the favorable response rate of neoplastic cells to the anticancer drugs." (PMID 34549887, 2021). "We thus believe that even though PPARβ and PPARγ were shown previously to have anti-proliferative, pro-apoptotic effects, their implication with regards to cancer is still unclear and warrants further investigation." (PMID 34360635, 2021). "MiR-3184-5p and miR-181c-3p targets forkhead box P4 (FOXP4), a gene involved in cancer growth and metastasis, and peroxisome proliferator-activated receptor alpha (PPARγ), known to be an oncogene." (PMID 34359591, 2021). "Both of these isoforms activate peroxisome proliferator-activated receptor γ (PPARγ) expression, which is known to control inflammation by inducing apoptosis and inhibiting cancer cell proliferation." (PMID 34211628, 2021). "In conclusion, these results suggest that Alp alleviates cancer cachexia progression and prevents muscle atrophy via activating PPARγ and thereby inhibiting phosphorylation of NF-κB and STAT3." (PMID 34093209, 2021). "PPAR has three different subtypes (PPARα, PPARβ/δ, and PPARγ) and has been shown to participate in the brain metastasis of cancer cells." (PMID 34530822, 2021). "PPARG (peroxisome proliferator-activated receptor gamma) is a protein-coding gene, which has been suggested to improve chemosensitivity in human carcinomas, including HSCC." (PMID 34054937, 2021). "PPARγ agonists have been also shown to function as an anticancer factors, especially for obesity related cancers as a prostate, breast, colon, liver, thyroid, lung, and pituitary cancers." (PMID 32710395, 2020). "In this study we investigated the apoptotic mechanism and the anti-cancer effects of a novel purine-based PPARγ agonist, CB11 (8-(2-aminophenyl)-3-butyl-1,6,7-trimethyl-1H-imidazo[2,1-f]purine-2,4(3H,8H)-dione), on human NSCLC cells." (PMID 32958825, 2020).